CCDC57 (coiled-coil domain containing 57)
Description:
Pleiotropic regulator of centriole duplication, mitosis, and ciliogenesis. Critical interface between centrosome and microtubule-mediated cellular processes. Centriole duplication protein required for recruitment of CEP63, CEP152, and PLK4 to the centrosome. Independent of its centrosomal targeting, localizes to and interacts with microtubules and regulates microtubule nucleation, stability, and mitotic progression.
Synonyms: FLJ00130; FLJ23754
Tractability: No criterion of Open Targets' tractability assessment is met for any kind of drug.
Gene: Protein-coding gene on chromosome 17 (82,101,459 to 82,212,878, reverse strand). Ensembl gene ENSG00000176155.
Subcellular location: Cytoplasm, cytoskeleton, microtubule organizing center, centrosome; Cytoplasm, cytoskeleton, microtubule organizing center, centrosome, centriolar satellite; Cytoplasm, cytoskeleton, microtubule organizing center, centrosome, centriole; Cytoplasm, cytoskeleton, spindle
Subcellular location (Human Protein Atlas): Microtubules; Centriolar satellite; Cytosol
Gene Ontology:
Molecular function: protein binding
Biological process: centriole replication; cilium assembly; G2/M transition of mitotic cell cycle; microtubule nucleation; positive regulation of mitotic cell cycle
Cellular component: centriolar satellite; centriole; centrosome; spindle microtubule; spindle
Genetic constraint (gnomAD): Loss-of-function variants: 111 observed, 103.13 expected, observed/expected ratio (o/e) 1.08, 90% interval 0.92 to 1.26. The upper end of that interval is the gene's LOEUF score, 1.26, which puts it in group 5 of 6, group 1 being the genes least tolerant of losing a copy. Missense variants: 1,267 observed, 1,231 expected, observed/expected ratio (o/e) 1.03, 90% interval 0.98 to 1.08. Synonymous variants: 515 observed, 499.51 expected, observed/expected ratio (o/e) 1.03, 90% interval 0.96 to 1.11.
Homologues: Orthologues: macaque CCDC57 (90% identical), chimpanzee CCDC57 (87% identical), rat Ccdc57 (62% identical), mouse Ccdc57 (61% identical), guinea pig CCDC57 (61% identical), pig CCDC57 (53% identical), dog CCDC57 (46% identical), tropical clawed frog ccdc57 (37% identical), Caenorhabditis elegans B0432.7 (8% identical). Paralogues in human: CCHCR1 (13% identical), CIP2A (10% identical).
Diseases named in the same sentence as CCDC57 in open-access papers:
CCDC57 is named in the same sentence as 10 diseases in open-access papers, as found by Europe PMC text mining. Sharing a sentence is not in itself a finding about the gene and the disease. The quoted sentences say what the papers report.
chronic kidney disease (1 paper, 2024). Impairment of the renal function secondary to chronic kidney damage persisting for three or more months. "Several genes that initially appeared significant without correction—such as PEAK1 for diabetes, TRIM10 for schizophrenia, and CCDC57 for chronic kidney disease—fell below the Bonferroni significance threshold after correction, underscoring the importance of this adjustment." (PMID 37904952, 2024).
gastric cancer (1 paper, 2020). A primary or metastatic malignant neoplasm involving the stomach. "The methylation of XKR6, CCDC57, MAML3, SDC2, and CLIP4 is associated with age and tumor location in gastric cancer." (PMID 33575272, 2020).
scoliosis (1 paper, 2023). A congenital or acquired spinal deformity characterized by lateral curvature of the spine. "In the following studies, we focused on the ccdc57Δ7 mutant allele to evaluate the function of Ccdc57 in spinal development and scoliosis." (PMID 36862758, 2023). "In this paper, we present data showing that deficiency of the centrosomal protein, Ccdc57, results in scoliosis in zebrafish." (PMID 36862758, 2023). "Here, we have characterized a late-onset zebrafish scoliosis mutant exhibiting loss of function of Ccdc57." (PMID 36862758, 2023).
situs inversus (1 paper, 2026). A congenital condition in which there is complete right-to-left reversal of the position of the major thoracic and abdominal organs (that is, they are arranged in a mirror image of the normal positioning). "Finally, we identified a patient with situs inversus carrying compound heterozygous CCDC57 missense variants." (PMID 41758249, 2026).
tumor (3 papers, 2017 to 2025). "The methylation of other genes, CLIP4, XKR6, CCDC57, MAML3 and SDC2, was related with one or more of the following variables: age, tumor location, and Helicobacter pylori infection, rather than with the histologic subtype." (PMID 28418867, 2017).
CCDC57 also shares sentences with these, for which no sentence is quoted: adolescent idiopathic scoliosis (1 paper); carcinoma (1); diabetes (1); Hydrocephalus (1); schizophrenia (1).